FOXP3 (forkhead box P3)
Diseases named in the same sentence as FOXP3 in open-access papers (continued):
Sharing a sentence is not in itself a finding about the gene and the disease.
ovarian carcinoma (continued). "Herein, R54 reduced Foxp3 and DNMT1 transcription, as previously reported in murine ovarian cancer, where the CXCR4 inhibitor, AMD3100, selectively reduced intratumoral Foxp3 Tregs and DNMT1 determining loss of Tregs suppressive function in vitro and in vivo." (PMID 38704478, 2024). "Our study provides compelling evidence that the modulation of FOXP3 gene expression in OVCAR3 cells by rosmarinic acid and doxorubicin represents a promising avenue for enhancing therapeutic strategies against ovarian cancer." (PMID 39770446, 2024). "Glypican-3, ALDH1A1, TNFR2, STAT3, FOXP3, and TIM3 are increasingly recognised biomarkers to predict chemoresistance in women with ovarian cancer." (PMID 36768291, 2023). "In advanced stage ovarian cancer, the presence of CD8+ cells, FoxP3+Treg or a high CD8/FoxP3 frequency ratio in tumor tissue was associated with an increased disease specific survival." (PMID 35634289, 2022). "Using the same dataset, we also observed high levels of PD‐L1, PD‐1, FOXP3, and E2F1 in the ovarian cancer samples that expressed high levels of SPHK1 compared to samples that expressed low levels." (PMID 35289120, 2022). "In the TME of ovarian cancer, the ratio of CD8+ T cells to Foxp3+ regulatory T cells was significantly high, which was associated with a particularly favorable prognosis." (PMID 34485300, 2021). "Six out of 20 genes (IFN-γ, Foxp3, IL-4, BCL-2, Oct4 and survivin) selected by the Laplacian score showed key roles in the development of ovarian cancer and their prognostic values were clinically and statistically confirmed." (PMID 34181334, 2021). "In ovarian carcinoma treated with NACT, local CD8+ cells increased while Foxp3+ cells remained stable." (PMID 30474571, 2018). "Some groups have demonstrated that in ovarian-cancer tumor-tissue sections, intraepithelial CD8+ TILs correlate with good outcome, and others have shown that a high ratio of CD8+/FoxP3+ T regulatory cells (Tregs) is beneficial to survival." (PMID 30200478, 2018). "In the ascites of ovarian cancer patients, the frequencies of IL-10+ B cells are also positively correlated with the frequencies of CD4+Foxp3+ Tregs." (PMID 27331871, 2016). "Other groups have isolated highly suppressive FoxP3+ Tregs expressing CTLA-4, GITR and TIM-3 from immune infiltrates of HCC, CRC, cervical and ovarian carcinomas." (PMID 27509527, 2016). "In hepatocellular carcinoma and ovarian cancer, GARP-expressing FoxP3+ Tregs were expanded in the peripheral blood and ascites, respectively." (PMID 26885615, 2016). "This study examined the tissue of 210 patients with ovarian carcinoma for the infiltration of CD8+ effector T-cells and FoxP3+ T regulatory cells (Treg)." (PMID 25365237, 2014). "Tregs in ovarian cancer commonly express high levels of CD4, CD25, and FOXP3." (PMID 40703514, 2025). "Moreover, ovarian cancers that were triply positive for intraepithelial CD4+, FOXP3+, and CD25+ cells showed a trend towards increased survival (p = 0.059)." (PMID 36768291, 2023). "Intending to define the exact cellular composition of ACTBL2-expressing leukocytes in ovarian cancer, various common markers for the most frequent immune cell subtypes have been investigated—CD4 (T-helper cells), FOXP3 (regulatory T-cells) and CD56 for natural killer cells." (PMID 38114558, 2023). "Similar to FOXP3, reducing the expression of CTLA-4 with RNA interference or TET inhibitors may improve ovarian cancer outcomes." (PMID 36428581, 2022). "In conclusion, the relative expression levels of CD8, FoxP3, and PD-L1 were significantly related to the clinical outcome of patients with HGSOC, which could be a kind of significant immunoprofiling of ovarian cancer patients to apply for treatment." (PMID 34502561, 2021). "Secondly, peripheral accumulation of FoxP3+ Treg cells in lymphoid clusters is a strongly significant negative prognostic factor for patients suffering from ovarian carcinoma." (PMID 25365237, 2014).
ovarian carcinoma (continued). "Conversely, FoxP3+ regulator T cells (Tregs), through their immunomodulatory role, have been correlated with therapeutic resistance and worse survival outcomes in many solid tumors, although their role in ovarian cancer is still not completely defined." (PMID 39248018, 2024). "Ascites-derived T cells from ovarian cancer patients have been reported to frequently express co-inhibitory receptors, which can lead to T cell dysfunction in ovarian cancer, and CD4+ T cells expressing the transcription factor FoxP3 usually favor tumor progression." (PMID 36607962, 2023). "In conclusion, the relative expression levels of CD8, FoxP3, and PD-L1 were significantly related to the clinical outcome of patients with HGSOC, showing that they could be a kind of significant immunoprofiling in ovarian cancer." (PMID 34502561, 2021). "For example, in ovarian cancer, tumor cells secrete CCL28 to recruit Tregs; hypoxia-inducible factor-1 (HIF-1) induced by hypoxia directly downregulates Foxp3 expression by combining with the Foxp3 promoter region, inducing Treg formation, and regulates the function and differentiation of MDSCs." (PMID 30813924, 2019). "Despite several early reports associating this subset of T regulatory cells with a poor outcome, a meta-analysis of 869 patients over several studies did not conclude that FoxP3 Tregs in the tumors of ovarian-cancer patients are a significant prognostic indicator of survival." (PMID 30200478, 2018). "In a previous study we could demonstrate that IL-17, but not FOXP3 positive immune cell infiltration in primary and recurrent ovarian carcinoma were indicative of chemosensitivity." (PMID 27531373, 2016). "In addition, “non-canonical” CD8+FOXP3+ cells seem to be involved in ovarian cancer progression." (PMID 28275576, 2017). "Interestingly, TGF-β, but not ovarian cancer conditioned medium, also promotes Il17a expression in CD4+IL-17A+ TALs, suggesting that TGFβ might be promoting IL-17A+Foxp3+ cells while the tumour microenvironment promotes exTh17 Foxp3+ T cells." (PMID 28290453, 2017). "Indeed, some studies have shown that FOXP3 expression is elicited in activated T cells with no regulatory activities, which could lead one to speculate that some of the CD4+CD25+FOXP3+ T cells in ovarian cancer may not be regulatory." (PMID 24244610, 2013).
rheumatoid arthritis (100 papers, 2006 to 2025). A chronic, systemic autoimmune disorder characterized by inflammation in the synovial membranes and articular surfaces. "More interestingly, sex-specific differences have been increasingly recognized and reported in FOXP3 genetic mutations involved in diseases, such as ulcerative colitis (UC), rheumatoid arthritis (RA) and Multiple Sclerosis (MS)." (PMID 36717877, 2023). "The importance of FOXP3 in regulating Tregs is supported by a study in which patients with rheumatoid arthritis, a chronic autoimmune disease exhibited an insufficient expression of FOXP3 inducing a deficiency in Tregs." (PMID 33614551, 2021). "In addition, evidence has indicated that Foxp3+ Treg cells can converse into inflammation-associated Th17 cells under proinflammatory conditions both in psoriasis and in rheumatoid arthritis (RA)." (PMID 32684837, 2020). "The imbalance between RORγt+ type 17 helper T cells (Th17) and FoxP3+ regulatory T cells (Treg) in synovial lesions plays a crucial role in the development of rheumatoid arthritis." (PMID 40429822, 2025). "The imbalance between RORγt+ type 17 helper T cells (Th17) and Foxp3+ regulatory T cells (Treg) in synovial lesions is a significant factor in the pathogenesis of rheumatoid arthritis." (PMID 39769163, 2024). "For example, KAT5 was lowly expressed in rheumatoid arthritis T cells, which affected regulatory T cell function via reducing Foxp3 acetylation level." (PMID 38561411, 2024). "As for PP1 can dephosphorylate Foxp3 at the Ser418 site in the C-terminal DNA-binding domain to decrease Treg-mediated suppressive function, particularly in the model of rheumatoid arthritis." (PMID 37936703, 2023). "Senescent Foxp3+CD4+CD28− T lymphocytes have been identified in patients with rheumatoid arthritis, which downregulate CD25 while showing increased expression levels of TNF-α and IL-17A in addition to decreased suppressive capacity." (PMID 35269683, 2022). "CD4+CD25+Foxp3+ regulatory T (Treg) cell-mediated immunosuppression is an essential mechanism of rheumatoid arthritis (RA)." (PMID 36064312, 2022). "discussed the intervention of regulatory T cells characterized by the expression of CD4+, CD25+, and Foxp3+ in patients with rheumatoid arthritis." (PMID 33791204, 2021). "A recent study described Treg perturbations in rheumatoid arthritis joints that are reminiscent of those described here (in particular with elevated FoxP3 MFI), an interesting parallel since the arthritic joint is high in IL-6." (PMID 34433692, 2021). "Ectopic expression of Tip60 restored FOXP3 levels, directing Treg differentiation and its suppressive activity in a model of rheumatoid arthritis." (PMID 33614551, 2021). "In rheumatoid arthritis and periodontitis, the presence of unstable Treg lymphocytes that have lost the expression of Foxp3 and their regulatory capacities have been described." (PMID 34341698, 2021). "An additional study that assessed ginger’s effects on rheumatoid arthritis demonstrated improvement by reducing symptoms via inducing FOXP3 gene expression." (PMID 31935866, 2020). "Previously, TNFα was shown to downregulate Treg function since the TNFα-blocking agent Infliximab increased FOXP3 expression and restored their suppressive function in rheumatoid arthritis (RA) patients." (PMID 29619032, 2018). "Regulatory T cells (Tregs, CD4+CD25+Foxp3+) exhibit immune suppressive effects in the immune system, regulate bone remodeling, and are closely linked to skeletal-related disease, such as osteoporosis and rheumatoid arthritis (RA)." (PMID 29675436, 2018). "But anti-TNF therapy of patients with active rheumatoid arthritis restored FOXP3 expression as well as suppressive function." (PMID 29619032, 2018). "In rheumatoid arthritis patients, the increase of FOXP3 transcripts including exon 2 exceeds that of FOXP3 transcripts excluding exon 2 in isolated CD4+ T cells from blood (2.3- to 3.2-fold) and synovial fluid (3.6-fold)." (PMID 29593749, 2018).
rheumatoid arthritis (continued). "Previous studies have shown that the inhibition of CD4+CD25+Foxp3+Tregs result in the functional impairment or decrease in the number of cells in various ADs such as multiple sclerosis (MS) and rheumatoid arthritis (RA)." (PMID 29191190, 2017). "In a mouse model of rheumatoid arthritis, Foxp3 fate reporter mice revealed that “exFoxp3+” cells converted toward Th17 cells under IL-6 exposure in the synovia and became highly osteoclastogenic." (PMID 26583099, 2015). "IL17+ Foxp3+ T cells were also detected in the synovia of patients with active rheumatoid arthritis." (PMID 26583099, 2015). "In contrast to this study, rheumatoid arthritis patients had significantly lower proportions of peripheral blood CD19+FoxP3+ B cells as compared to healthy controls, particularly in patients with interstitial lung disease." (PMID 26504851, 2015). "Here, we discuss the phenotypes and function of Foxp3+ Treg cells and the potential use of such Treg cells against rheumatoid arthritis (RA)." (PMID 25152867, 2014). "When infliximab has been used to treat patients with active rheumatoid arthritis, the population of Treg cells that express forkhead box P3 (Foxp3) has increased." (PMID 22546542, 2012). "Gancao Fuzi decoction may regulate the imbalance of Th17/Tregs in rheumatoid arthritis by promoting Foxp3 protein expression through the inhibition of miR-34a gene expression." (PMID 41458964, 2025). "Moreover, 50, 100, and 200 μg/mL OLE promote the expansion of CD4+CD25+FoxP3+ T regulatory cells (Tregs) in both healthy controls and rheumatoid arthritis patients after 24 h." (PMID 37446206, 2023). "Specifically, identification of increased numbers of IL-17+Foxp3+ Treg cells in the synovium of individuals with active rheumatoid arthritis, suggests that plastic Foxp3+ Treg cells contribute to the pathogenesis of rheumatoid arthritis." (PMID 34539668, 2021). "Furthermore, rheumatoid arthritis (RA) patients treated with methotrexate (MTX), which reduces the level of DNMT1, were characterized by restored Tregs functions and higher Foxp3 expression caused by a decrease in upstream enhancer methylation." (PMID 34281195, 2021). "Contrary to studies on other autoimmune conditions, such as rheumatoid arthritis, Foxp3+ and IL-10+ Bregs were not negatively associated with autoantibodies in Graves’ patients." (PMID 34681587, 2021). "Moreover, in a mouse model (collagen induced) of rheumatoid arthritis, FOXP3 transduction led to inhibition of T-cell activation and attenuation of the cell proliferation." (PMID 27887663, 2016). "Subsequently, FOXP3 loses its transcription repression of IL-2 and Treg cells lose their suppressive function, causing increased numbers of IL-17+ and IFN-γ+CD4+ T cells within the inflamed synovium of rheumatoid arthritis patients." (PMID 26441996, 2015). "Additionally, TNFα has been shown to lead to FOXP3 dephosphorylation and consequent inhibition of Treg suppressive activity in rheumatoid arthritis patients." (PMID 25770018, 2015). "Thus, our data seem to be more in line with data from mice suggesting that the interaction of TNF-α with TNFR2 on Tregs promotes their expansion and upregulation of FOXP3 than with the data from studies of human rheumatoid arthritis." (PMID 19343213, 2009). "Interestingly, the inflammatory milieu present in both rheumatoid arthritis and periodontitis-affected tissues is able to provoke Treg phenotypic instability, substantially downregulating their Foxp3 and CD25 expression, the hallmarks of their regulatory phenotype." (PMID 35269683, 2022). "MTX can enhance the generation of adenosine through FOXP3 T + reg cells to moderate the immunotolerant environment to ameliorate rheumatoid arthritis (RA) damage." (PMID 36355499, 2022).
rheumatoid arthritis (continued). "The purpose of this study was to examine whether BV phospholipase A2 (bvPLA2), an enzymatic component of BV, is a novel anti-inflammatory and anti-arthritic mediator capable of stimulating CD25+ Foxp3+ regulatory T cell (Treg) polarization in a mouse model of human rheumatoid arthritis (RA)." (PMID 33568685, 2021). "Additionally, using a mouse model of rheumatoid arthritis, the Komatsu group described that Th17 cells with autoimmune properties can be generated from Foxp3+ regulatory T cells in vivo, demonstrating that the instability of Treg can lead to pathological conditions." (PMID 26583087, 2015). "As increases in peripheral Foxp3+ Tregs have also been reported for patients with cancer, primary Sjögren’s Syndrome and rheumatoid arthritis, psoriasis and systemic sclerosis, we hypothesize that a non-specific chronic inflammatory mediator can cause this effect." (PMID 23874626, 2013). "Treatment of patients with rheumatoid arthritis (RA) with antibodies against the IL-6 receptor resulted in the skewing of T-cell differentiation towards Foxp3+ Tregs and away from Th17 cells." (PMID 26344346, 2013). "When FOXP3 expression was measured, a significant increase was found both in the combination and full dose anti-TNFα groups, underscoring likely effects of both therapeutic regimens on some Treg functions, in accordance with recent findings in Rheumatoid Arthritis patients." (PMID 17183718, 2006). "Previous reports show that IL-1 and IL-6 alone and together downregulate FOXP3 while inducing IL-17 expression on Tregs in a STAT3-dependent way; this is also apparent in EAE and rheumatoid arthritis." (PMID 38386413, 2024). "The study of rheumatoid arthritis(RA) revealed that diminished levels of TIP60 disrupt the acetylation process protecting the FOXP3 protein, leading to impaired functionality of FOXP3+Tregs and promoting Th17 differentiation." (PMID 39144146, 2024). "Mechanistically, in rheumatoid arthritis (RA), naïve CD4+CD45RO- T produces fewer Foxp3 proteins, which results in the differentiation of naïve T cells into Th17 commitment, while leads to fewer Treg populations, which affects the Th17/Treg balance." (PMID 37936703, 2023). "Morbidly obese hASCs inhibited the proliferation of CD3 T cells, derived from rheumatoid arthritis (RA) patients, in a dose-dependent fashion, however, they promoted that of CD4+ FOXP3+ T cells." (PMID 37462786, 2023). "Kaempferol has also been shown to prevent and treat inflammatory diseases such as rheumatoid arthritis and SLE by increasing FOXP3 expression in Treg cells or reducing PIM1-mediated FOXP3 phosphorylation at S422." (PMID 37026113, 2023). "Furthermore, we show that CD69+FoxP3+ and TIGIT+FoxP3+ Treg subsets are induced by VD3-primed DCs, which are especially beneficial for the targeted suppression of pathogenic Th17 cell responses that contribute to disease progression in psoriasis and rheumatoid arthritis, among others." (PMID 35874744, 2022). "Likewise, inclusion of exon 2 in FOXP3 mRNAs significantly increases in blood from coronary artery disease patients compared to healthy controls and the same trend is seen in blood from patients with autoantibodies, rheumatoid arthritis, and biopsies from inflammatory bowel disease patients." (PMID 29593749, 2018). "Lastly, ASH1L, FOXP3 and SMAD3 are downregulated in peripheral CD4+ T cells from patients with rheumatoid arthritis." (PMID 28598443, 2017). "In studies conducted in patients with active rheumatoid arthritis, peripheral blood CD4+CD25+ Tregs have shown reduced FOXP3 expression and suppressive function which can be reversed by treatment with an anti-TNFα monoclonal antibody (infliximab)." (PMID 24063002, 2013). "Compared to healthy controls, FOXP3 transcripts lacking exon 7 increase in synovial fluid of rheumatoid arthritis as well as in peripheral blood and biopsies from Crohn’s disease patients." (PMID 29593749, 2018).